ASAH1 (N-acylsphingosine amidohydrolase 1)
Diseases named in the same sentence as ASAH1 in open-access papers (continued):
Sharing a sentence is not in itself a finding about the gene and the disease.
Progressive myoclonic epilepsy (23 papers, 2017 to 2025). "Mutations in ASAH1 cause two different disorders: Farber disease (FD) and spinal muscular atrophy combined with progressive myoclonic epilepsy (SMA-PME)." (PMID 38397161, 2024). "This woman, whose lower limb weakness started at 14 years old, presented a pure motor phenotype without epileptic myoclonic seizures, contrary to the classical phenotype associated with ASAH1 mutations named SMA with progressive myoclonic epilepsy (SMA-PME)." (PMID 37337091, 2024). "Patient 15 was detected with an 8.5 kb heterozygous deletion involving exon 1 of the ASAH1 gene which is known to be associated with autosomal recessive spinal muscular atrophy with progressive myoclonic epilepsy [MIM159950]." (PMID 35495136, 2022). "Mice with the P361R mutation in the lysosomal ceramidase, Asah1, exhibit a spinal muscular atrophy with progressive myoclonic epilepsy (SMA-PME)-like phenotype and may be a valuable tool to evaluate future therapies for SMA-PME." (PMID 37231125, 2023). "Mutations in both enzymes lead to progressive myoclonic epilepsy, whereas specific mutations in the ASAH1 gene were found to cause spinal muscular atrophy with progressive myoclonic epilepsy, suggesting a link between dysregulation of sphingolipid metabolism and epilepsy." (PMID 32111095, 2020). "Interestingly, a rare epileptic disorder known as spinal muscular atrophy with progressive myoclonic epilepsy (SMA-PME) is also associated with ASAH1 deficit." (PMID 34202192, 2021). "Moreover, mutations in ASAH1 are also associated with a form of spinal muscular atrophy that also features progressive myoclonic epilepsy (SMA-PME)." (PMID 29163032, 2017). "In addition, mutations in ASAH1, which result in dysfunctional acid ceramidase, cause a non-5q form of SMA associated with progressive myoclonic epilepsy." (PMID 36143200, 2022). "Mutations in the ASAH1 gene can lead to two different rare diseases, the lysosomal storage disorder Farber disease (FD) and an epileptic disorder called spinal muscular atrophy with progressive myoclonic epilepsy (SMA-PME)." (PMID 36094170, 2022).
breast cancer (19 papers, 2011 to 2025). A primary or metastatic malignant neoplasm involving the breast. "In breast cancer, ASAH1 expression correlates with lymph node metastasis, although conflicting reports exist regarding its prognosis association." (PMID 38926346, 2024). "Consistent with its role in metabolizing ceramide, ASAH1 has been shown to be overexpressed in some cancer types and predict poor prognosis in gastric cancer and disease progression in breast cancer." (PMID 33766731, 2021). "In breast cancer, over-expressed ASAH1 was found in estrogen receptor (ER)-positive patients compared to ER-negative patients." (PMID 32236130, 2020). "Even though ASAH1 and SPHK1 are sequential enzymes of the same pathway and have been functionally linked high ASAH1 expression has been associated with a positive outcome in epithelial ovarian and estrogen receptor positive breast cancers." (PMID 24970218, 2014). "ASAH1 overexpression in breast cancer is associated with lymph node metastasis." (PMID 33766731, 2021). "Additionally, MCL has been demonstrated to counteract tamoxifen resistance in breast cancer (BC) by downregulating the expression of Amidohydrolase 1 (ASAH1), adjusting the ROS/AKT signaling pathway, and activating the NRF2/KEAP1 antioxidant mechanism." (PMID 40051564, 2025). "We observed ASAH1 to be overexpressed in breast cancer patient samples but not in normal adjacent breast tissue samples." (PMID 38926346, 2024).
spinal muscular atrophy (19 papers, 2017 to 2025). A motor neuron disease that affect the muscles, and characterized by muscle weakness and atrophy resulting from progressive degeneration and irreversible loss of the anterior horn cells in the spinal cord (i.e., lower motor neurons) and the brain stem nuclei. "Additionally, mutations in the ASAH1 gene have also been described in a subset of spinal muscular atrophy patients." (PMID 31835809, 2019).
lysosomal storage disorder (18 papers, 2011 to 2025). "Acid ceramidase (ACDase) deficiency is an ultrarare autosomal recessive lysosomal disorder caused by pathogenic N‐acylsphingosine amidohydrolase (ASAH1) variants." (PMID 37962265, 2023). "Hypofunctional ASAH1 mutations cause Farber’s disease, a rare lysosomal disorder characterized by articular deformation, subcutaneous nodules and progressive hoarseness." (PMID 33806766, 2021). "Interestingly, loss-of-function mutations in the Ac gene (human, ASAH1; mouse, Asah1) result in a lysosomal storage disorder named Farber granulomatosis or Farber disease (FD)." (PMID 38919612, 2024). "This process is fundamental since ASAH1 is prominently involved in a genetic lysosomal storage disorder in human (Farber’s disease)." (PMID 33884955, 2021). "For example, for ASAH1 (N-acylsphingosine amidohydrolase 1) in the sphingomyelin disorder, which is a sub-type of phospholipidosis, our map shows that inactivated ASAH1 participates in the ‘hypofunction of ceramide degradation’ process." (PMID 32883995, 2020).
acute myeloid leukemia (15 papers, 2018 to 2023). Acute myeloid leukemia (AML) is a group of neoplasms arising from precursor cells committed to the myeloid cell-line differentiation. "Similarly, ASAH1 has been shown to cause drug resistance in acute myeloid leukemia and radio resistance in glioblastoma cells." (PMID 33766731, 2021).
glioblastoma (13 papers, 2017 to 2024). The most malignant astrocytic tumor (WHO grade IV). "This led to the identification of overexpression of ASAH1 as a potential biomarker associated with glioblastomas and the development of anticancer therapy." (PMID 32290213, 2020). "Proteomic analysis of more than 600 glioblastoma-specific proteins revealed, for the first time, that expression of acid ceramidase (ASAH1) is associated with poor glioblastoma survival." (PMID 29348854, 2017). "Due to its high level of expression in GSCs, ASAH1 inhibition is proposed as a new anti-glioblastoma therapy that specifically targets GSCs." (PMID 29348854, 2017). "Here, we report that ASAH1, having the best correlation with survival of all studied proteins, is negatively correlated with glioblastoma survival." (PMID 29348854, 2017). "Tissue specimens from nine patients with newly diagnosed glioblastoma were subjected to immunohistochemical (IHC) staining of ASAH1." (PMID 29348854, 2017). "This study has discovered both ASAH1 as a de novo glioblastoma drug target and a new class of drug tailored towards GSCs, given ASAH1 is highly expressed only in CD133+ GSCs." (PMID 29348854, 2017). "Carmofur is an ASAH1 inhibitor that crosses the blood-brain barrier, a major bottleneck in glioblastoma treatment." (PMID 29348854, 2017). "Strikingly, U87MG cells, and three different patient-derived glioblastoma stem-like cancer cell lines were efficiently killed, through apoptosis, by three different known ASAH1 inhibitors with IC50's ranging from 11–104 μM." (PMID 29348854, 2017). "ASAH1 is identified as a de novo glioblastoma drug target, and ASAH1 inhibitors, such as carmofur, are shown to be highly effective and to specifically target glioblastoma GSCs." (PMID 29348854, 2017). "In addition, modification of ASAH1 in glioblastoma enables it to be secreted to interstitial tissues, allowing it to transfer their malignant potential to nearby cells." (PMID 32290213, 2020). "Previous studies have shown that glioblastomas express ASAH1 in high numbers." (PMID 32290213, 2020). "Given that the previous study has identified CD133+ cells as actual glioblastoma stem-like cells, we speculate that ASAH1 may decrease overall survival by enhancing survival of GSCs, and therefore, producing resistance to common anticancer therapies." (PMID 29348854, 2017). "ASAH1 levels are also elevated in the subpopulation of GBM cells known as glioblastoma stem-like cells, which express the neural and brain cancer stem cell marker CD133, which in turn is associated with poor prognosis if expressed at high levels." (PMID 31906280, 2020). "However, none has implicated ASAH1 to play a significant role in the cancer biology of glioblastoma." (PMID 29348854, 2017). "Thus, ASAH1 inhibitors are gaining interest in cancer therapy and were found to trigger apoptosis in cancer cells; in this regard, ASAH1 inhibitors were shown to be effective in killing glioblastoma cancer stem cells as well as head and neck cancer cells (HNC)." (PMID 34102611, 2021). "Although there are no drugs in clinical trials targeting ceramide signaling for glioblastomas, ASAH1 inhibitors (carmofur, N-oleoylethanolamine, and ARN14988) have been studied against multiple glioblastoma stem cell lines, U87, and patient-derived cell lines." (PMID 32290213, 2020). "Temozolomide, the only FDA-approved glioblastoma chemotherapy agent, has a minimal effect (~20% cell death) on U87MG cells at 72 hours compared to ASAH1 inhibitors." (PMID 29348854, 2017). "CD133+ GSCs express significantly higher ASAH1 compared to CD133- GSCs and serum-cultured glioblastoma cell lines, such as U87MG." (PMID 29348854, 2017). "The exclusive secretion of ASAH1 by CD133+ GSCs can be utilized as an advantage by developing an antibody or tumor vaccine against the secreted ASAH1, allowing a therapy specifically targeting glioblastoma." (PMID 29348854, 2017).
glioblastoma (continued). "In recurrent glioblastoma (GBM), elevated ASAH1 levels is observed and treatment of temozolomide (TMZ)-resistant GBM cells with carmofur resulted in decreased cell growth migration and invasion and increased apoptosis." (PMID 38926346, 2024).
glioma (11 papers, 2017 to 2026). A benign or malignant brain and spinal cord tumor that arises from glial cells (astrocytes, oligodendrocytes, ependymal cells). "Based on our understanding of ASAH1 in primary gliomas and the association of ASAH1 with chemoresistance in other tumors, we sought to determine if ceramidases were elevated in recurrent gliomas." (PMID 38086808, 2023). "Based on the high expression of ASAH1 mRNA in glioma patients, we sought to determine if TMZ-resistant GBM cells are sensitive to carmofur, a pharmacologic inhibitor of ASAH1." (PMID 38086808, 2023). "Using The Cancer Genome Atlas (TCGA), we found that ASAH1 was elevated in MGMT unmethylated gliomas, but the other ceramidases were unchanged." (PMID 38086808, 2023). "ASAH1 is overexpressed in glioma tissue from patients compared to normal brain, while the other ceramidases remain unchanged." (PMID 38086808, 2023). "Elevated ASAH1 mRNA was also significantly associated with worse survival for all glioma patients (GBM and low-grade gliomas)." (PMID 35741006, 2022). "The CD133-expressing glioma TICs were found to overexpress acid ceramidase (ASAH1), and several inhibitors of this enzyme efficiently induced apoptosis in these TICs." (PMID 31661927, 2019). "Given its important role in cancer formation, prior studies have suggested ASAH1 as a novel anti-cancer target in other non-central-nervous-system cancers." (PMID 28445970, 2017). "Earlier studies have shown that ASAH1 is strongly expressed in glioma cells." (PMID 40942013, 2025). "Notably, it easily crosses the blood-brain barrier and is a potent inhibitor of ASAH1, making it a worthy drug for investigation in the case of gliomas." (PMID 36012521, 2022). "ASAH1 has been shown to be an important drug target in regulating the growth of GBM cells and glioma like-stem cells." (PMID 29642535, 2018). "Although no clinically approved drugs currently exist that directly target ceramide signaling in gliomas, several ASAH1 inhibitors—such as carmofur, N-oleoylethanolamine, and ARN14988—have demonstrated efficacy in vitro across multiple glioma cell lines, including U87 and patient-derived cells." (PMID 40942013, 2025). "When we assessed the expression of available ceramidases (ACER1 was unavailable) in primary and recurrent gliomas using the Chinese Glioma Genome Atlas (CGGA), we found that only ASAH1 was increased in recurrent gliomas while the other ceramidases were unchanged." (PMID 38086808, 2023). "Notably, the antitumor activity of ASAH1 inhibitors has surpassed that of temozolomide (TMZ)—an FDA-approved chemotherapeutic—suggesting that pharmacological inhibition of ASAH1 may increase ceramide accumulation in tumor tissue and induce apoptosis in glioma cells." (PMID 40942013, 2025).
cystic fibrosis (10 papers, 2014 to 2024). Autosomal recessive disorder caused by pathogenic variants in the CFTR gene (cystic fibrosis transmembrane conductance regulator), which encodes a chloride and bicarbonate channel expressed in epithelial cells, and follow the diagnosis criteria. "To analyze the role of acid ceramidase in cystic fibrosis, we generated mice that lack functional Cftr and overexpress acid ceramidase (mouse gene, Asah1)." (PMID 33139382, 2021).
colorectal cancer (9 papers, 2017 to 2024). A primary or metastatic malignant neoplasm that affects the colon or rectum. "In colorectal cancer (CRC), ASAH1 overexpression is linked to immunological cell death induction, enhancing the antitumor immune response." (PMID 38926346, 2024). "First, significant differences in gene expression between normal tissue and colorectal cancer tissue were observed for ASAH1, ACER3, CERS2, and CERS6." (PMID 37758931, 2023). "Carmofur, a potent ASAH1 inhibitor that has been used to treat colorectal cancer in some countries, selectively reduced the viability of TSC2-null cells in a dose-dependent manner (IC50 = 17 μM) and to a lesser extent TSC2-addback cells (IC50 = 253 μM)." (PMID 36927688, 2023). "Among these three known inhibitors of ASAH1, carmofur, which is capable of crossing the blood-brain barrier, is already a common treatment modality for colorectal cancers in Japan since 1981." (PMID 29348854, 2017). "Studies of carmofur activity in colorectal cancer cells, patients with colorectal carcinoma, glioblastoma cells, and breast cancer cells demonstrate that carmofur is effective in suppressing ASAH1 expression." (PMID 36927688, 2023). "In addition, Carmofur, an ASAH1 inhibitor, was approved to be against colorectal cancer in Japan." (PMID 36936425, 2023). "For example, we observed the enhanced DEGS2's consumption amount of dhCer as reported in colorectal cancer, the significantly inhibited salvage pathway by overexpressed CERS5, and the activated sphingosine generation pathway by overexpressed ASAH1." (PMID 37999228, 2023). "Carmofur, a derivative of 5-fluorouracil, inhibits acid ceramidase (ASAH1), a key enzyme in the production of S1P, and is in use outside the USA to treat colorectal cancer." (PMID 38086808, 2023).
Krabbe disease (9 papers, 2020 to 2023). A lysosomal disorder that affects the white matter of the central and peripheral nervous systems. "Lack of either ASA, GALC, or ASAH1 results in a fatal lysosomal storage disease designated as metachromatic leukodystrophy (MLD; OMIM 250100), globoid cell leukodystrophy (Krabbe disease; OMIM 245200), and Farber disease (OMIM 228000), respectively." (PMID 34375644, 2021).
lung carcinoma (9 papers, 2011 to 2023). "ASAH1 is a long gene that has been found associated with lung cancer and Farber's Disease, and there are 14 tagged SNPs in high LD and 9 of them are in complete LD (majority of pair-wise R2>0.71)." (PMID 22174922, 2011). "To understand whether the interplay between STING and S1P in lung cancer tissues was associated with patients’ overall survival, we considered the median values of ASAH1 (median = 4.643) and STING (median = 2.767) transcripts in lung tumor tissues as reported in the TCGA_LUAD_2016 database." (PMID 37176007, 2023). "To understand at what stage STING and ASAH1 were correlated, we took advantage of a mouse model of carcinogen-induced lung cancer, in which chronic inflammation is at the basis of the malignant transformation." (PMID 37176007, 2023). "Functional experiments showed that inhibiting ASAH1 suppressed the proliferation, migration, and invasion of lung cancer cells." (PMID 32236130, 2020). "ASAH1 is the most studied ceramidase; we have demonstrated its involvement in lung cancer." (PMID 37446018, 2023). "Notably, some of the nine differential proteins (3HAO, ASAH1, CHMP5, FPRP, IBP3, MERTK, MUC18, NRP1, and PRIO) in tumor-forming rats have already been reported to be associated with lung cancer biomarkers/pathology/mechanisms or ovarian cancer metastasis." (PMID 32678190, 2020). "Further, through function experiments in lung adenocarcinoma cell lines in vitro, we found that ASAH1 could be an oncogene, and thus inhibiting ASAH1 can suppress the proliferation, migration, and invasion of lung cancer cells." (PMID 32236130, 2020). "Collectively, these results suggest that ASAH1 could be an oncogene, and thus inhibiting ASAH1 can suppress the proliferation, migration, and invasion of lung cancer cells." (PMID 32236130, 2020). "Thus, this could lead us to suppose that the activation of ASAH1 worsens lung cancer patients’ survival, mainly due to the activation of fatty acid metabolism, which we already demonstrated to be altered in lung cancer, as well as proto-oncogene pathways." (PMID 37176007, 2023). "The functional significance of ASAH1 and TAOK2 in lung cancer cells was evaluated." (PMID 32236130, 2020). "Lung cancer patients positive to STING and ASAH1 mRNA levels had a dismal prognosis in that the overall survival was reduced compared to STING/ASAH1 negative patients." (PMID 37176007, 2023).
colon cancer (7 papers, 2017 to 2023). "Inhibiting ASAH1 in colon cancer using carmofur sensitized cells to oxaliplatin, a platinum-based chemotherapy." (PMID 38086808, 2023).
brain tumor (6 papers, 2017 to 2023). "To examine the role of ASAH1 in survival of pediatric brain tumor cells, we used previously identified ASAH1 inhibitors N-oleoylethanolamine (OE) and carmofur." (PMID 28445970, 2017). "To test the effectiveness of ASAH1 inhibitors at targeting pediatric brain tumors, we treated these pediatric brain tumor cell lines with known ASAH1 inhibitors, carmofur and OE." (PMID 28445970, 2017). "Finally, inhibiting the migration of cancer cells by blocking ASAH1 may be a promising avenue for metastatic brain tumors." (PMID 35741006, 2022). "The mechanism involved in the regulation of ASAH1 may have been altered in the CD133+ GSCs, allowing it to be secreted into culture media or possibly into the interstitial tissues in case of an in vivo brain tumor." (PMID 29348854, 2017).